BRAF (B-Raf proto-oncogene, serine/threonine kinase)
Diseases named in the same sentence as BRAF in open-access papers (continued):
Sharing a sentence is not in itself a finding about the gene and the disease.
tumor (continued). "We found a concordant pattern between primary tumours and related distant metastatic sites in 34 out of 37 cases for K-Ras, in all cases for BRAF and in 34 out of 38 cases for PTEN." (PMID 19293803, 2009). "We observed similar trends in the likelihood of response between patients with BRAF-mutant or BRAFWT tumours (0 vs 17%)." (PMID 19603024, 2009). "A further sample was positive for a BRAF mutation in which initial analysis had been negative with a high ΔCt; this sample was from a patient known to have a BRAF+ tumour." (PMID 19861964, 2009). "Nine patients randomised to temozolomide had a confirmed partial response, three of whom had BRAF+ tumours." (PMID 19861964, 2009). "The aim of this study is to analyse molecular alterations predictive for anti-EGFR therapies response, such as EGFR gene status, K-Ras and BRAF mutations, and PTEN protein expression, in primary tumour and synchronous or metachronous metastasis." (PMID 19293803, 2009). "AZD6244 is an orally available, potent, selective, ATP-uncompetitive inhibitor of MEK1/2, with pre-clinical activity in BRAF mutation-positive (BRAF+) and RAS mutation-positive tumour models." (PMID 19861964, 2009). "Six patients randomised to AZD6244 had a confirmed partial response, of whom five had BRAF+ tumours." (PMID 19861964, 2009). "In contrast to knock-down of PIK3CA in HCT116, nude mice bearing subcutaneous tumors resulting from injected HCT116 BRAF-inducible shRNAs cells, when treated with dox showed a delay in tumor growth." (PMID 19492075, 2009). "Subsequent to revealing the differential BRAF status of the tumour areas, the study of the profiles of 330 miRNAs in the areas provided further insight into multifocal cancer." (PMID 19055826, 2008). "Tumours were obtained from patients of US (n=143) and Korean (n=167) origin and screened for LKB1, KRAS, BRAF, and EGFR mutations using RT—PCR-based SURVEYOR-WAVE method followed by Sanger sequencing." (PMID 18594528, 2008). "BRAF mutations occur in about 10 to 18% of CRC overall and in 30 to 45% of MSI CRC, more frequently in tumours harbouring MLH1 promoter hypermethylation and with a CpG island methylation phenotype (CIMP)." (PMID 18782444, 2008). "As our findings in NSCLC cell lines suggested concurrency of KRAS or BRAF and mutual exclusiveness of EGFR mutations with LKB1 mutations, we analysed the mutational status of these genes in our primary NSCLC tumour specimens." (PMID 18594528, 2008). "Important distinctions between tumours that express RET/PTC vs BRAF V600E are their relationships to radiation exposure and age at PTC diagnosis." (PMID 17179987, 2007). "The BRAF mutation is found in comparable proportions in French (36%, 5/14) and CTB tumours (41%, 5/12)." (PMID 17712314, 2007). "CIMP-high colorectal tumors appear to have a distinct clinical, pathologic and molecular profile, including associations with female sex, proximal tumor location, poor differentiation, microsatellite instability (MSI) and BRAF mutation." (PMID 17474983, 2007). "In vitro and in vivo models have demonstrated that overexpression of activated BRAF induces malignant transformation and aggressive tumour behaviour." (PMID 17179987, 2007). "Gene-expression signatures separating BRAF from RET/PTC tumours have been reported, but the number of genes involved varies from a few dozens to several thousands." (PMID 17712314, 2007). "Recently Rossi reported three cases of MTC/PTC collision tumour in which two mutations, in the RET and BRAF genes, were identified, thus documenting the different genetic origin of these two coexisting carcinomas." (PMID 17997826, 2007).
tumor (continued). "It is also possible that the discordant aspirate material in the present study contained only the BRAF WT genotype, and that the mutant DNA identified in the resected tumor samples was the result of an early tumorigenic event." (PMID 16606457, 2006). "Six had V600E-positive tumours (n=4 had PD; n=1 had SD; n=1 unevaluable for response), and 11 had tumours containing wild-type BRAF (n=9 PD; n=1 SD; n=1 unevaluable for response)." (PMID 16880785, 2006). "Only one wild-type BRAF-positive tumour biopsy was derived from a patient with SD, nine were from patients with PD, and one from an unevaluable patient." (PMID 16880785, 2006). "In our cohort, EGFR-inhibiting antibodies may have been used alone or combined with chemotherapy to enhance response in inoperable, locally advanced RAS- and BRAF-wildtype tumours." (PMID 41511558, 2026). "Also, in a murine syngeneic tumor model, inhibition of BRAF signaling enhanced production of IFNγ and TNFα and increased MHC class I and II expression on tumor cells." (PMID 41514118, 2026). "Tumor sidedness and molecular alterations such as RAS and BRAF mutations are established prognostic factors in mCRC; however, their role in VTE risk stratification remains unclear." (PMID 41751211, 2026). "In ALM, where canonical oncogenic mutations such as BRAF V600E and NRAS Q61 are less frequent, EZH2-driven epigenetic mechanisms may play an even more dominant role in tumor initiation and progression." (PMID 42220432, 2026). "ECOG performance status, smoking status, primary tumor location, number of metastatic organs, number of systemic therapy lines received, and BRAF mutation status did not significantly differ between cohorts (all p > 0.05)." (PMID 41598406, 2026). "In addition to genetic mutations such as BRAF^V600E^ and NRAS, lipid metabolic reprogramming has emerged as a critical factor in tumor progression and therapy resistance." (PMID 41596686, 2026). "Together, these findings support tumor-wide upregulation of the TIGIT/CD155 axis in CRC and suggest that TIGIT, more than CD155, tracks with MSI/BRAF-associated immune activation, providing a rationale for patient stratification in checkpoint-directed immunotherapy." (PMID 41596586, 2026). "Increasing evidence indicates that oncogenic drivers, including EGFR, ALK, KRAS, MET, RET, and BRAF, actively shape the tumor immune microenvironment (TIME) by regulating antigen presentation, immune cell infiltration, cytokine signaling, metabolic programs, and immune checkpoint expression." (PMID 42079655, 2026). "Somatic mutations in KRAS, NRAS, BRAF, and the occurrence of microsatellite instability (MSI) were assessed using pyrosequencing and real-time PCR assays, respectively, on formalin-fixed, paraffin-embedded tumour samples." (PMID 42279292, 2026). "Although exploratory in nature, the signal suggests that BRAF-driven tumor biology may be far less common in H/L individuals within this clinical context." (PMID 41516350, 2026). "We evaluated sequential tumor biopsies during therapy to test the hypotheses that BRAF/MEKi would increase TIL and lead to an expansion of functional intratumoral tumor‐reactive CD8 T‐cells and TIL clonality in the tumor microenvironment." (PMID 41514118, 2026). "As these neoplasms tend to be BRAF non-mutated, they are most often treated with immune checkpoint inhibitors." (PMID 40506928, 2025). "From a technical standpoint, liquid biopsy is already well‐established to determine RAS or BRAF gene mutations and readily can be applied if tumor tissue is not available." (PMID 39630848, 2025). "Comprehensive Sanger sequencing of the resected tumor tissue revealed no mutations in the TERT promoter or the BRAF V600E gene." (PMID 40013148, 2025). "BRAF downregulation links to EAPP mutants affecting tumor growth and patient outcomes." (PMID 41009348, 2025).
tumor (continued). "In “negative hyperselected” patients, the absence of resistance-associated mutations (e.g., KRAS, NRAS, BRAF V600E, and EGFR extracellular domain mutations) ensures that the EGFR pathway remains a primary driver of tumor progression, making these tumors more susceptible to EGFR blockade." (PMID 40076838, 2025). "In addition to a high CpG island methylator phenotype, factors such as high microsatellite instability, BRAF/RNF43 mutations, consensus molecular subtypes, and high tumor mutational burden are also correlated with decreased mRNA expression of SATB2." (PMID 40636538, 2025). "Furthermore, there is a significant reduction in the overall survival in CRC patients with a mutated BRAF/MEK/PI3K oncogenic signature, underlining its role in tumor aggressiveness and resistance to therapy." (PMID 41009348, 2025). "In a recent multicentre analysis, BRAF-mutated tumours fared poorly after CRS–HIPEC regardless of PCI or CCR status." (PMID 41300980, 2025). "They confirmed the significant correlation between Fn and BRAF p.V600E somatic mutation and CIMP-high CRC, yet the Fn enrichment in hereditary cancers also indicates the importance of the MMR-deficient tumour microenvironment for the colonization, irrespectively of the origin of the defect." (PMID 40297307, 2025). "However, pharmacological inhibition of the MAPK pathway with MEK or BRAF inhibitors successfully restored iodine uptake, leading to tumor regression after RAI therapy." (PMID 41368991, 2025). "The combination of high-throughput assays aimed at identifying the common mutations such as BRAF, RET, and RAS and at evaluating ctNAs can provide important information about the mutational spectrum of the tumor and guide the selection of appropriate targeted therapy." (PMID 40095491, 2025). "Hence, pan-HDAC inhibition can affect and impair tumor cell survival through the promotion of apoptosis in various BRAF-mutant tumor models." (PMID 39935431, 2025). "Molecular profiling through next-generation sequencing (NGS) is essential for therapeutic planning; in our patient, the tumor was negative for BRAF, NRAS, and KIT mutations." (PMID 40937205, 2025). "The BRAF V600E mutation activates the MAPK/ERK pathway, driving abnormal proliferation and impaired differentiation of SOX2 + cells, which likely serve as the cellular basis for tumor initiation." (PMID 40696244, 2025). "Similarly, targeted inhibition of B-Raf proto-oncogene, serine/threonine kinase) (BRAF) signaling can induce initial tumor regression but often leads to metabolic rewiring and reactivation of survival pathways, ultimately promoting recurrence." (PMID 41614770, 2025). "Ulixertinib demonstrates potent anti-tumor activity in preclinical studies using cell lines and xenograft models with mutations in BRAF, RAS, and MEK genes, as well as in cases of acquired resistance to BRAF and MEK inhibitors." (PMID 41373605, 2025). "The parallel associations with BRAF-mutated and CIMP+ tumours suggested that it may be involved in the development of sporadic MMR defects." (PMID 40297307, 2025). "As BRAF-mutant pMMR CRCs are known to show a particularly aggressive behavior with reduced survival outcomes, these findings underscore that SARIFA-positivity is linked to an aggressive tumor biology." (PMID 40340947, 2025). "It should be noted that although dabrafenib (150 mg orally twice daily) and trametinib (2 mg orally daily) have been used for BRAF V600E‐positive tumours in these trials, the doses in concomitant cases are still unknown." (PMID 39950095, 2025). "Agreement between tumor tissue BRAF V600E status and plasma ctDNA BRAF V600E was 84.3%." (PMID 39859576, 2025).
tumor (continued). "We found that PDOs obtained from patients with a left-sided RAS/BRAF-WT tumor (n = 9) were more sensitive to EGFR inhibitor panitumumab, compared with PDOs obtained from patients with right-sided and/or RAS/BRAF-mutant tumors (n = 15; median-normalized GRAUC, 0.59 vs. 0.81; P = 0.012)." (PMID 40982295, 2025). "The BRAF V600E mutation, common in PTC, is linked to aggressive features, and its allele frequency (AF) may serve as a biomarker for tumor aggressiveness." (PMID 40805249, 2025). "For instance, aggressive therapy which aims to completely eliminate all tumor cells may put increased evolutionary pressure on the tumor, leading to resistance within months, as has been seen with BRAF/MEK inhibitors." (PMID 40002300, 2025). "While NF1 and CBL mutations may contribute to tumor initiation in EOCRC, BRAF-driven signaling appears to play a more prominent role in LOCRC." (PMID 40282501, 2025). "Limiting analyses to BRAF (V600) mutant tumours, 23 patients receiving initial PD‐1 therapy and 32 patients receiving initial BRAF + MEK therapy could be assessed." (PMID 40331873, 2025). "However, autophagy is a double-edged sword, playing either a pro-tumor or tumor-suppressive role in BRAF-mutant cancers." (PMID 39935431, 2025). "However, prognosis also depends on the tumor grade and underlying molecular alterations, such as mutations in KRAS, BRAF, and GNAS." (PMID 40746921, 2025). "Additionally, some research has indicated that LDHA inhibitors in conjunction with BRAF inhibitors have demonstrated notable anti-tumor activity in ATC therapy." (PMID 40917751, 2025). "The other case with BRAF V600E mutations was treated with vemurafenib after failure of etoposide, prednisone, vincristine, cyclophosphamide, and doxorubicin (EPOCH) chemotherapy, showing significant decrease in tumor size and metabolic activity." (PMID 40943476, 2025). "The tumour’s BRAF status does not correlate with prognosis, whereas mutations in the TERT promoter gene have prognostic implications." (PMID 40831998, 2025). "Binoculars identified specific mutations frequently showing significant allelic imbalance in many affected tumors; for instance, 75 of the significant BRAF p.V600E mutations, predominantly in SKCM, showed a mean tumor VAF of 0.57 suggesting strong selections of the mutant allele via amplification." (PMID 41415395, 2025). "Interestingly, indolent thyroid neoplasms like FAs and encapsulated follicular-patterned neoplasms typically lack the BRAF:p.V600E molecular alteration and show RAS-like molecular profile." (PMID 40940966, 2025). "Notably, acetoacetate displayed unique roles in cancer cells, including the promotion of tumor growth in BRAF-V600E+ cancer cells through the activation of MEK-ERK signaling and induction of FGF21 expression in HepG2 cells." (PMID 39554048, 2025). "High CD8 + tumor-infiltrating lymphocytes observed in BRAF-mutant CRC suggest that these patients may respond well to immunotherapy." (PMID 40991561, 2025). "FoundationOne next-generation sequencing showed that her PD-L1 tumor proportion score was 0%, tumor mutation burden was low, and there were no reportable alterations in BRAF, ERBB2, KRAS, or NRAS." (PMID 40026534, 2025).
tumor (continued). "Targeted therapies might also enhance the presentation of tumor antigens to immune cells, improving the priming of tumor-specific T cells as well as targeting EGFR, VEGFR, or BRAF, which are frequently mutated or dysregulated in GI cancers." (PMID 40943055, 2025). "NGS of this tumor specimen was again negative for BRAF, KIT, NF1, and NRAS mutations, but was again notable for a missense mutation in EZH2 (c.2075 C > T, p.A692V)." (PMID 39984702, 2025). "In parallel, comprehensive molecular profiling of the tumor tissue was performed to identify potentially actionable genomic alterations; however, no targetable mutations (e.g., BRAF, NRAS, c-KIT) were identified, thereby limiting the use of targeted therapies." (PMID 41384184, 2025). "GDC-0879 was primarily reported as a BRAF mutant inhibitor, and may exert opposing cellular context-dependent functions on tumor growth." (PMID 40781221, 2025). "This realization led to the VE-BASKET trial, one of the first tumor-agnostic studies to enroll patients based on the presence of BRAF V600E mutations regardless of histology." (PMID 41153346, 2025). "Notably, BRAF-targeted therapy elevates tumor cell PD-L1 expression, exacerbating T cell exhaustion." (PMID 40861443, 2025). "La implementación de la detección de BRAF V600E en las instituciones de salud podría consolidarse a futuro como una herramienta clave en la oncología de precisión, optimizando así el diagnóstico y tratamiento de diversas neoplasias." (PMID 40977817, 2025). "Instead, the absence of mutations in KRAS, NRAS, and BRAF and other mechanisms determine tumor dependency on EGFR signaling." (PMID 40940901, 2025). "KRAS and BRAF mutations were determined by regular diagnostics for all patients, with half determined on metastatic tissue and the other half on primary tumor tissue, not necessarily from the same lesion as the PDO biopsy." (PMID 40982295, 2025). "In Patient 6, a class III BRAF p.D594N (kinase-impaired) with additional MAP2K1 activating mutation (requiring RAS activation) was detected in the primary tumor but not in the metastasis." (PMID 39912776, 2025). "However, bona fide tumor-associated activating mutations in RAC1 have been identified, with the RAC1P29S hotspot mutation associated with resistance to BRAF-targeted therapies." (PMID 39636745, 2025). "BRAF p.Val600Glu mutations were found in three left‐sided and 1 right‐sided tumour, NRAS p.Gln61Lys in 1 right and 1 left‐sided tumour, KRAS p.Lys147Glu and p.Ala146Thr in one left‐sided tumour, and HRAS p.Ala121Thr in the tumour of the rectum." (PMID 40302146, 2025). "In several preclinical tumor systems with Class II and III BRAF mutations, exarafenib, a novel type 2 pan-RAF inhibitor that binds RAF proteins irrespective of isoform or dimerization state, demonstrates robust anti-tumor activity." (PMID 41282105, 2025). "Although KRAS mutations are generally unrelated to LNM status or tumor characteristics, our study demonstrates a shift in KRAS mutation rates across the two LNM-negative subtypes, potentially offering survival benefits to CRC patients with BRAF mutations." (PMID 40991561, 2025). "Although this study reinforced the association between BRAF:p.V600E and certain aggressive tumor features, it did not directly assess the recurrence or mortality outcomes in PTC cases." (PMID 40940966, 2025). "In this case, the tumor showed BRAF mutation at the time of lung metastasis, and 131 I was not effective." (PMID 40502629, 2025). "To investigate whether mannose enhanced the anti-tumor effect of PLX4032 in BRAF-mutated ATC, we treated the BRAF-mutated ATC cell lines 8305C and 8505C with increasing doses of PLX4032, both with and without mannose supplementation." (PMID 40063000, 2025). "Interestingly, complete concordance for hotspot driver mutations, such as BRAF V600 and NRAS Q61K, between tumor and ctDNA samples occurred even at low SNV burdens, with individual VAFs ranging from 0.2% to 28%." (PMID 39859576, 2025).